MSH6 (mutS homolog 6)
Diseases named in the same sentence as MSH6 in open-access papers (continued):
Sharing a sentence is not in itself a finding about the gene and the disease.
cancer (continued). "An older median age at diagnosis was observed for cancers in path_MSH6 and path_PMS2 carriers." (PMID 37181409, 2023). "Interestingly, in our local cohort, within MMR-D cancers, we found high MSH6 protein expression in 38/104 patients." (PMID 36482191, 2023). "Moreover, we found that both the two nonsense mutations in MSH6 were caused by a G > T transversion in AGA context, which was a representative characteristic of pathogenic POLE EDMs related cancers as confirmed in several previous studies." (PMID 36765365, 2023). "Moreover, among the interaction network of cohesin subunits, many proteins are known to be involved in cancer or adenocarcinoma pathways, such as mutS homolog 6 and phosphatidylinositol-4,5-bisphosphate 3-kinase catalytic subunit alpha." (PMID 35371307, 2022). "Among identified or obligate carriers of the MSH6 c.3936_4001+8dup (intronic) variant alone, no cancer tissue samples were available to resolve the pathological role for this variant." (PMID 36612224, 2022).
cancer (continued). "Our data are in line with previous reports that cancers with MSH6 germline variants often display low or absent MSI1,56." (PMID 34145315, 2021). "The impact of a heterozygous RECQL4 mutation on cancer predisposition unknown, particularly in the context of simultaneously inherited DNA damage and repair gene mutations like BAP1 and/or MSH6." (PMID 33541411, 2021). "In this study, we determined the potential role of “DNA replication”, “mismatch repair”, “cell cycle”, “ATPase activity” and DNA metabolism in the etiology or pathogenesis of cancer through a series of enrichment analyses on MSH6-binding protein and MSH6 expression-related genes across all tumors." (PMID 34941572, 2021). "Several emerging cell- or animal-based studies have verified that MSH6 mutations are closely linked to the occurrence, progression or metastasis of cancer, but there is still no practicable pan-cancer analysis." (PMID 34941572, 2021). "Three (75%) of four cancers detected in MSH6 carriers were classified as high risk, but no cancers were detected in MSH6 non-carrier controls to enable a comparison." (PMID 34678156, 2021). "Three cancers were MSI-high and one case with isolated MSH6 loss was MSS in PCR analysis." (PMID 32108923, 2020). "The MSH6 knockout signature is most similar to COSMIC signature 20 with cosine similarity of 0.91, although there are relatively high cosine similarities when compared to other cancer-derived signatures associated with MMR-deficiency (all ⩾0.6)." (PMID 29717121, 2018). "We however do not know if the relatives with LS-associated cancers also carried this specific MSH6 sequence variant." (PMID 28531214, 2017).
cancer (continued). "There was no family history of cancer reported in the patient harboring the MSH6 deletion, while the patients carrying the MLH1 variant has a sister diagnosed with EC and CRC." (PMID 26811195, 2016). "The patients carrying the MSH6 and MLH1 variants had EC diagnosed years later than the average age of cancer development in LS patients (60 and 57 years of age, respectively) and neither of the two were carriers of any additional variants that was considered to be of significance." (PMID 26811195, 2016). "Although clinical data suggested the presence of a pathogenic mutation in the respective families, our results indicate that none of the three MSH6 variants can be held responsible for cancer predisposition." (PMID 24040339, 2013). "We therefore aimed to evaluate the contribution of germline MSH6 mutations for early-onset CRC in patients without a family history of HNPCC-related cancer." (PMID 16940983, 2006). "In addition, studies of MSH6 mutant mice have shown that these mice have significantly increased cancer susceptibility and that the tumors in these mice do not exhibit repeat instability, similar to the results observed in yeast." (PMID 40469174, 2025). "As the MSH6 gene contains a microsatellite of eight mononucleotide repeats, it is likely that a secondary somatic mutation in these microsatellites of the MSH6 gene is a potential mechanism for the complete or partial loss of MSH6 immunoexpression in already MMR-deficient cancers." (PMID 36387226, 2022). "An interesting still remaining question is whether or not cancers with multiple HRR mutations as our MLH1-/PMS2-/MSH6- cases are more likely to benefit from PARP-inhibitor therapy than those with only a single HRR mutation." (PMID 36387226, 2022).
cancer (continued). "In the integrated germline and somatic assessment presented here, germline variants in MSH6 and PMS2 were assessed with the combination of MMR/MSI/IHC/LOH and personal clinical findings, all of which collectively elucidate a likely involvement of the germline variant in patient cancer." (PMID 36091175, 2022). "We found that the cancer-associated fibroblasts’ estimated infiltration value for the TCGA tumors of ESCA, HNSC (HPV -) and PAAD analyzed based on all algorithms was statistically positively related with the expression of MSH6, and only negatively related in TGCT tumors." (PMID 34941572, 2021). "No cancer was detected in patients with MSH6 or PMS2 mutations." (PMID 33916129, 2021). "TCGA project and GEO database were used to perform pan-cancer analysis of MSH6 for the first time, and systematically described the expression differences, prognostic value, protein phosphorylation as well as relevant cellular pathways of MSH6 in different cancer types." (PMID 34941572, 2021). "Path_MSH6 and path_PMS2 carriers do not have an increased risk for cancer before 40 years of age." (PMID 28874130, 2017). "Moreover, we describe two Lynch families in which MSH6 variants do not fully segregate with the cancer phenotype and discuss the clinical implications of this finding." (PMID 28481244, 2017). "The MIN analysis data implies that the Msh6 defect-mediated MIN by itself may not be responsible for tumorigenesis but that it may provide cancer predisposition." (PMID 23734346, 2013). "Interestingly, we did not detect any mutation in TGFBR2, MSH3, or MSH6 microsatellite sequences in rectal or sigmoid MSI-H carcinomas in our test series." (PMID 20979647, 2010). "However, MSH6 mutations may be involved in 5% of all HNPCC families and give rise to atypical HNPCC with a delayed onset of cancer." (PMID 16106253, 2005). "Our results, taken together with our previous similar findings concerning six other missense mutations in MSH6 and the clinical data of the patients and their families, lead us to conclude that most missense changes in MSH6 cause no or low cancer susceptibility." (PMID 15354210, 2004). "Lastly, promoter methylation of MSH6 and TUMP3 have also been found to correlate with IBD-related dysplasia and cancer." (PMID 41562706, 2026).
cancer (continued). "Three LS cases were missed with MMR IHC (1 MSH6 and 2 PMS2 carriers), it is possible these patients had sporadic cancers unrelated to their LS carrier status." (PMID 39886913, 2025). "The most commonly overexpressed genes in rare cancers included BIRC5 (88%), TOP2A (85%), CDK4 (82%), BRIP1 (76%), MSH6 (66%), and HDAC2 (62%)." (PMID 38347552, 2024). "Carriers of path_MSH6 had substantially lower CRC incidence and the cancers occurred predominantly after 50 years of age." (PMID 37181409, 2023).